LINC01719 (long independently transcribed non-coding RNA 1719)
Gene: Long non-coding RNA gene on chromosome 1 (146,052,566 to 146,061,952, forward strand). Ensembl gene ENSG00000233396.
Diseases named in the same sentence as LINC01719 in open-access papers:
LINC01719 is named in the same sentence as 2 diseases in open-access papers, as found by Europe PMC text mining. Sharing a sentence is not in itself a finding about the gene and the disease.
LINC01719 shares sentences with these, for which no sentence is quoted: bladder cancer (1 paper); tumor (1).